BIRC5 (baculoviral IAP repeat containing 5)
Diseases named in the same sentence as BIRC5 in open-access papers (continued):
Sharing a sentence is not in itself a finding about the gene and the disease.
cancer (continued). "Baculoviral inhibitor of apoptosis repeat-containing 5 (BIRC5, also called survivin) is a member of the inhibitor of apoptosis protein (IAP) family, which plays an important role in the occurrence and progression of cancer." (PMID 29147412, 2015). "Since Survivin/BIRC5, the smallest member of the IAP-family which is structurally characterized by only a single BIR domain, has been identified and demonstrated to be overexpressed in cancer tissues, it has attracted increasing interest." (PMID 23755220, 2013). "The cancer-specificpromoter BIRC5 and non-specific CMV immediately early gene promoter were usedfor comparison." (PMID 24303203, 2013). "Targeting BIRC5 could offer a novel strategy for improving HCC treatment outcomes, paving the way for more effective therapeutic interventions against this aggressive cancer." (PMID 40471223, 2025). "Moreover, BIRC-5, KNTC-1, MCM2, MKI-67, PCNA, and E2F4 genes were downregulated in HCT-116 cancer cell lines, and there was no significant change in the expression of the same genes in HT-29 cancer cell lines." (PMID 40872562, 2025). "The BIRC5 gene is active in different cancers but not in normal tissues." (PMID 36145609, 2022). "Because of selective expression in tumor but not normal tissues, for over a decade, BIRC5 has drawn considerable attention as a potential novel drug target in a variety of human cancers and has consistently been demonstrated to be a critical factor in tumor progression." (PMID 34804966, 2021). "The expression of BIRC1 and BIRC5 significantly varied across LUAD stages, and the expression of BIRC5 significantly varied across LUSC stages, suggesting that these IAPs may serve as potential biomarkers for diagnosis and cancer staging in NSCLC patients." (PMID 34925455, 2021). "Study in ovarian cancer cell lines (SKOV3 and OVCAR3 cells) has shown that the inhibition of BIRC5 gene by an inhibitor YM155 can significantly inhibit epithelial-mesenchymal transition (EMT) to prevent cancer metastasis, which contributes to the treatment and prognosis of cancer patients." (PMID 34112092, 2021). "Therefore, we speculate that BIRC5, as a oncoprotein, participates in the biological process of cancer through EMT, further affecting the prognosis of cancer patients." (PMID 34112092, 2021). "However, overexpression of cancer-related genes; EDN1 and BIRC5 in CSCs have been detected, suggesting that there is another networking pathway which triggering the activation of these genes which led to the enhancement of stemness characteristics of putative CSCs populations." (PMID 33995625, 2021). "The six hub genes (BIRC5, TOP2A, FANCI, NCAPG2, RAD51, and RRM2) were reported to be critical to regulate cell cycle, and their abnormal expression could lead to development and progression of cancers." (PMID 32902196, 2020). "One possible explanation could be that survivin (gene: BIRC5), an inhibitor of apoptosis that is overexpressed in cancer but not in normal tissues, is also influenced by microgravity." (PMID 33317046, 2020). "Moreover, activation of several FGF downstream signaling pathways was also observed including cancer related pathways (RAS-MAPK, PIK3-AKT, and STAT) with a significant upregulation of several key molecules in these pathways (e.g., BIRC5, RAF1, MYCN, IGF2, SNAI2, POSTN)." (PMID 31477684, 2019). "Additionally, exposure to mifepristone downregulated the expression of several apoptotic genes, including BIRC5 and HELLS, while increased the expression of SLC7A11, a transporter involved in ferroptosis, an iron-dependent cell death that has been shown to be regulated in PDAC and other cancers." (PMID 36359879, 2022). "Furthermore, cisplatin treatment of CAFs caused a negative association of colony area with BIRC5 and EGF, and a positive association of colony area with NANOG expression in cancer cells treated by CMCAF_post-cisplatin medium, which was not seen in CMCAF cocultured cells." (PMID 33671869, 2021).
cancer (continued). "Only the expression profiles of CTA genes from the known TAA (NY-ESO-1 and MAGE-A12) and BIRC5, but not ERBB2, displayed elevated cancer expression with low healthy tissue expression." (PMID 36943460, 2023). "Combination of the BIRC5 inhibitor YM155 and EZH2 inhibitors achieved remarkable synergistic effect in cancer cell killing and this is independent of the canonical functions of EZH2 in methylating H3K27." (PMID 36612203, 2022). "Between BIRC5 and BIRC7, both positive and negative correlations were observed across the 32 cancers, demonstrating a histology dependent co-expression pattern." (PMID 31964418, 2020). "Survivin, or baculoviral inhibitor of apoptosis (BIRC5), is a protein belonging to the inhibitor of apoptosis (IAP) family of proteins; it is expressed in embryonal tissues, upregulated in human cancer cells and absent in most normal tissue." (PMID 33322413, 2020). "Unlike BIRC5 and BIRC7 which demonstrated a strong oncogenic role, BIRC6 tended to function as a tumor suppressor since it was down-regulated in eight human cancers." (PMID 31964418, 2020). "While it is noteworthy to discover another potential indication for the use of YM155 to treat cancers, we sought to understand better how YM155 exerts its negative effects on Birc5/Survivin expression." (PMID 30909651, 2019). "Gene expression analysis showed that clonogenic side population cells in cancers express genes involved in the cell cycle and mitosis (e.g., SKA1, CCNB1, CDC25C, CDC2, BIRC5, CENPE, AURKB, KIFs, TOP2A, ASPM) more strongly than non-side population cells." (PMID 23962337, 2013). "However, to the best of our knowledge, no targeted agents against UBE2T, UBE2C, BIRC5, or USP9X, either approved or in development, can be found in The Drug Gene Interaction Database or Genomics of Drug Sensitivity in Cancer database, while the only USP7 inhibitor, P22077, has not been tested in BC." (PMID 33671201, 2021).
tumor (374 papers, 2007 to 2026). "The results of univariate Cox regression analysis showed that there were significant differences in survival between AST, childpugh, tumor size, vascular invasion, BIRC5, EPO and risk groups." (PMID 40458412, 2025). "For B cells, CD20+, CD22+, ADAM28+, and BIRC5 have been identified within tumor‐associated TLSs and are implicated in enhancing the response to ICI therapy." (PMID 41235705, 2025). "Genes such as THY1, FN1, and BIRC5 function as diagnostic markers and demonstrate significant correlations with immune cell infiltration and tumour growth, indicating their dual involvement in disease identification and therapeutic intervention." (PMID 40475773, 2025). "The location of this variant in the promoter region of BIRC5 (rs8073069 G/C) reinforces its functional potential, as it has been linked to the expression of survivin, an apoptosis inhibitor implicated in tumor progression." (PMID 40725442, 2025). "BIRC5 stimulates cellular apoptosis, diminishes the growth capacity of tumours, and renders cancerous cells more susceptible to chemotherapeutic agents (e.g., etoposide, Taxol, cisplatin), immunotherapy, and gamma radiation." (PMID 38364254, 2024). "The level of cell proliferation-associated genes, FOXM1 and BIRC5 genes, was expressed less in the miR-18a/low tumours (p < 0.05)." (PMID 38786043, 2024). "Aberrant expression of BIRC5 is strongly associated with increased tumor cell proliferation, enhanced resistance to apoptosis, and treatment resistance." (PMID 39703228, 2024). "Studies have shown that BIRC5 is over expressed in over 60 types of tumors and is strongly linked to the differentiation, proliferation, infiltration, and metastasis of tumor cells." (PMID 38556560, 2024). "Both FOXM1 and BIRC5 are implicated in driving tumour progression by increasing the cell proliferation rates." (PMID 38786043, 2024). "A strength of our study was the ability to exclude BIRC5 from the PAM50 algorithm (the research version of the Prosigna assay) to independently assess BIRC5/survivin as a high-risk biomarker in breast cancer and its relationship with tumor subtype." (PMID 38515208, 2024). "In both studies, BIRC5 was associated with high-risk populations, including participants with aggressive tumor subtypes, advanced stage and larger tumors." (PMID 38515208, 2024). "This study shows that the expression of BIRC5 is positively associated with immune cell infiltration, indicating an “immune hot” tumor phenotype." (PMID 38832035, 2024). "BIRC5, prominently overexpressed in virtually all human malignancies, is strongly associated with a spectrum of aggressive tumor characteristics." (PMID 39308922, 2024). "After additional adjustment for tumor characteristics (e.g., ER status and tumor stage), BIRC5-high remained significantly associated with young age, Black race, ER status, and tumor size." (PMID 38515208, 2024). "Our study aimed to investigate the phytochemical constituents of TCM for their potential modulatory effects on BIRC5, a gene implicated in tumor progression." (PMID 38283837, 2023). "It effectively impedes tumor cell proliferation and hinder disease progression by diminishing anti-apoptotic associated Birc5 marker." (PMID 38045808, 2023). "High expression of BIRC5 has been associated with a worse prognosis, tumor stage, and response to therapy in survival and clinicopathology studies." (PMID 37426635, 2023). "Macrophages, CD8 T cells, and Th2 cells, the most crucial tumor-associated immune cells, were predicted significantly correlated with BIRC5 levels in the TCGA-LUAD cohort." (PMID 36046648, 2022). "The LC-BC CCPs formed have no more than 12 nodes and identified only seven genes (EDNRB, CDKN2A, VEGFD, FOS, GNG11, TGFBR2, and BIRC5) compromised in signaling pathways associated with the acquisition of tumor characteristics." (PMID 36101460, 2022).
tumor (continued). "Survivin, which is encoded by the BIRC5 gene, plays an essential role in inhibiting apoptosis, regulating the cell cycle, and regulating the anti-tumor activities of T cells." (PMID 35356211, 2022). "Many studies have assessed the relationship between BIRC5 polymorphisms and the occurrence of neoplasms." (PMID 35326407, 2022). "Recently, a study identified an association between BIRC5 expression and tumor-infiltrating lymphocytes (TILs)." (PMID 35331169, 2022). "BIRC5 (baculoviral IAP repeat containing 5 or survivin), shown to be upregulated in many tumour types including HNSCC, is associated with DNA methyltransferases and multiple immune cells infiltration." (PMID 35326543, 2022). "We found that high expression of BIRC5 was associated with higher tumor grades, histological type, IDH mutation status, 1p/19q chromosome co-deletion, and primary therapy outcome." (PMID 35309512, 2022). "It has to be mentioned though that splice variants (DEx3 and 2B) have been reported to have specific roles in some tumor cells and that the existence of splice variants represents another layer of regulation for BIRC5." (PMID 33413657, 2021). "Dysregulation of the Wnt/β-catenin signaling favors the upregulation of BIRC5/Survivin which is implicated in inhibiting caspases mainly caspase-3 and caspase-7 thus preventing apoptosis leading to the immortality of tumor cells." (PMID 34630850, 2021). "Higher BIRC5 expression was also strongly associated with worse patient survival and advanced tumor stage." (PMID 31964418, 2020). "Among all the IAPs, BIRC5 was the most predictive gene of tumor stage accounting for 12 of the significant associations (38%), all of which were positive associations which agreed with previous publications." (PMID 31964418, 2020). "TN adenocarcinoma patients in the BIRC5 high-expression group suffered from a significantly high risk of distant metastasis (P = 0.046), advanced N stage (P = 0.033), and tumor-bearing (P = 0.031) and deceased status (P = 0.003)." (PMID 31093306, 2019). "Survivin (encoded by BIRC5), an inhibitor of apoptosis, has been widely studied in malignancies, and high expression of survivin is a hallmark of virtually all human tumours including TGCTs53,54." (PMID 31235829, 2019). "Survivin gene, i.e BIRC5, expression is upregulated in many human tumors and this correlates with metastatic spread, tumor invasiness, and poor prognosis associated with treatment resistance." (PMID 25974963, 2015). "Increased expression of BIRC5 has been associated with chemotherapy resistance, enhanced proliferation, increased tumor recurrence and shorter patient survival." (PMID 18522746, 2008). "Furthermore, BIRC5 expression in gastric cancer demonstrated significant associations with gross morphology, depth of invasion, presence of distant metastases, tumor necrosis, metastatic stage, and vascular invasion." (PMID 39308922, 2024). "Since BIRC5 is reported to be an immune-associated gene that promotes tumor progression, many studies related to survivin in NSCLC focus on the sensitization to chemotherapy, radiotherapy, and targeted therapy, with little success achieved due the heterogeneity of this disease." (PMID 37509650, 2023). "Further immune analysis discovered that the BIRC5 mRNA expression was associated with the presence of immune cells in the tumor and the expression of immune checkpoint genes, indicating that BIRC5 may influence the immunological condition of PCa patients." (PMID 37077837, 2023). "In this study, the BIRC5 promoter region was substantially methylated, and hypermethylation was associated with higher mRNA expression with a Beta median value of 0.582 vs. 0.691 for control and tumor, respectively (p < 1 × 10−12)." (PMID 36358602, 2022).
tumor (continued). "The association between BIRC5 levels and tumor-infiltrating cells levels was estimated." (PMID 36046648, 2022). "As a result, BIRC5 represents a risk factor for tumor growth that may be predicted, and it may also be a potential therapeutic target in the treatment of TNBC." (PMID 36358602, 2022). "Moreover, rs2071214 located in the exon 4 of the BIRC5 gene is identified as a risk factor of tumor pathogenesis." (PMID 35685607, 2022). "Moreover, we explored the underlying evidence indicating that BIRC5 regulates immune cell infiltration in the tumor microenvironment in LGG patients." (PMID 35309512, 2022). "In addition, CGN expression was negatively associated with the tumor-promoting factors BIRC5 and CXCR4." (PMID 35223987, 2022). "Interestingly, BIRC5, a gene located at 17q and encodes survivin, was remarkably upregulated in the resistant tumor cells; its association with tumor cell proliferation property; makes it a potential target for refractory MCL." (PMID 34001881, 2021). "STRING and Cytoscape were used to determine whether the BIRC5 and its associated tumor transcription factors predicted before were functionally related to MDM2." (PMID 33195412, 2020). "In addition, elevated BIRC5 levels have been found to be associated with histological grade, tumor size, and TNM stage in HCC patients." (PMID 31534853, 2019). "Although no clear correlations between the expression level and patient outcome were observed here, the genes TOP2A, ETV4 and BIRC5 are interesting candidate targets for the 17q gain associated with poor outcome, but further validation is required on a larger tumor set." (PMID 18522746, 2008). "Moreover, Li et al24 showed that Birc5 deficiency could lead to increased CD3+ T lymphocytes in tumor sites and remarkable HCC suppression." (PMID 37326143, 2023). "BIRC5 is believed to promote tumor cell replication, invasion, and metastasis through cell cycle dysregulation and abrogating cellular death." (PMID 40422257, 2025). "The role of CCL2, HAVCR2, and BIRC5 in immune modulation and tumour progression present potential therapeutic targets." (PMID 40683913, 2025). "EZH2, PCNA, and BIRC5 were predominantly expressed in epithelial clusters, supporting their tumor-intrinsic roles." (PMID 40678068, 2025). "Reduction of the biomarker survivin/BIRC5 with upregulation of the differentiation antigen CK20 in circulating tumor cells (CTC), strongly correlated with plasma concentrations of drug (R = 0.97), demonstrating on target efficacy." (PMID 40361430, 2025). "BIRC5, an anti-apoptotic gene, exhibited an inverse correlation with regulatory T cells, suggesting its role in inhibiting anti-tumour immune responses." (PMID 40475773, 2025). "Our study demonstrates that resistance of mesenchymal-like TNBC cells is associated with down regulation of BIRC5 (survivin) and upregulation of CXCL8/IL-8 and M-CSF while that of epithelial tumor cells is associated with upregulation of CTSS, MCP-1 and DKK-1." (PMID 41279138, 2025). "As Survivin (also known as BIRC5) is known to play a crucial role in inhibiting tumor cell apoptosis, researchers have further examined the effect of sodium butyrate on Survivin." (PMID 40297576, 2025). "BIRC5 knockdown increased NK cell proliferation but reduced function, potentially aiding tumor survival." (PMID 39859485, 2025). "Three of the TAAs (BCAN, PTPRZ1, BIRC5) are highly over-expressed in GBM tumours compared with healthy tissue (except testis)." (PMID 41051649, 2025). "BIRC5 had the lowest gDS score, suggesting that its absence significantly affects tumour cell viability." (PMID 40591061, 2025).